CPNE6 (copine 6)
Description:
Calcium-dependent phospholipid-binding protein that plays a role in calcium-mediated intracellular processes. Binds phospholipid membranes in a calcium-dependent manner (By similarity). Plays a role in dendrite formation by melanocytes.
Synonyms: N-copine; copine-6
Tractability: Antibody: its Gene Ontology location is reachable by antibodies, with high confidence; UniProt places it where antibodies can reach, with medium confidence. PROTAC: its protein half-life has been measured.
Gene: Protein-coding gene on chromosome 14 (24,070,837 to 24,078,100, forward strand). Ensembl gene ENSG00000100884.
Subcellular location: Cytoplasm; Cell membrane; Endosome; Cytoplasmic vesicle, clathrin-coated vesicle; Perikaryon; Cell projection, dendrite
Subcellular location (Human Protein Atlas): Golgi apparatus; Vesicles
Pathways (Reactome):
Metabolism: Glycerophospholipid biosynthesis
Gene Ontology:
Molecular function: protein binding; calcium ion binding; phosphatidylserine binding; protein-membrane adaptor activity; calcium-dependent phospholipid binding
Biological process: positive regulation of dendrite extension; cellular response to calcium ion; glycerophospholipid biosynthetic process
Cellular component: extracellular exosome; axon; cytoplasm; dendrite; endosome; membrane; perikaryon; plasma membrane; clathrin-coated vesicle
Genetic constraint (gnomAD): Loss-of-function variants: 33 observed, 68.43 expected, observed/expected ratio (o/e) 0.48, 90% interval 0.36 to 0.64. The upper end of that interval is the gene's LOEUF score, 0.64, which puts it in group 2 of 6, group 1 being the genes least tolerant of losing a copy. Missense variants: 576 observed, 734.79 expected, observed/expected ratio (o/e) 0.78, 90% interval 0.73 to 0.84. Synonymous variants: 296 observed, 282.56 expected, observed/expected ratio (o/e) 1.05, 90% interval 0.95 to 1.15.
Homologues: Orthologues: macaque CPNE6 (99% identical), mouse Cpne6 (98% identical), rat Cpne6 (98% identical), rabbit CPNE6 (97% identical), guinea pig CPNE6 (97% identical), pig CPNE6 (97% identical), chimpanzee CPNE6 (97% identical), zebrafish cpne8 (46% identical), Caenorhabditis elegans nra-1 (40% identical), Caenorhabditis elegans gem-4 (38% identical), Caenorhabditis elegans cpna-2 (37% identical), Caenorhabditis elegans cpna-4 (25% identical), and 1 more. Paralogues in human: CPNE7 (65% identical), CPNE4 (61% identical), CPNE3 (52% identical), CPNE2 (50% identical), CPNE5 (49% identical), CPNE8 (49% identical), CPNE1 (48% identical), CPNE9 (46% identical).
Diseases named in the same sentence as CPNE6 in open-access papers:
CPNE6 is named in the same sentence as 19 diseases in open-access papers, as found by Europe PMC text mining. Sharing a sentence is not in itself a finding about the gene and the disease. The quoted sentences say what the papers report.
depression (8 papers, 2018 to 2025). "Copine-6 is associated with conditions such as epilepsy and depression, with elevated expression in the temporal lobes of patients with temporal lobe epilepsy and reduced expression in the hippocampus of rat models of depression." (PMID 40537608, 2025). "Taking together with their important role in linking neuropsychiatric behaviors to synaptic plasticity, these results indicated that BDNF-related imbalance expression of Copine-6 and synapse plasticity-associated proteins play a vital role in the depression-like behavior induced by LPS challenge." (PMID 32009956, 2019). "For example, quercetin attenuates LPS-induced depression-like behavior and learning memory impairment in rats, which may be related to its modulation in the imbalance of hippocampal Copine 6 and TREM1/2 expression associated with brain-derived neurotrophic factor." (PMID 35369029, 2022). "Furthermore, there are several reports stating that Copine 6 is decreased in depression animal models, which is also the antidepressant target of quercetin." (PMID 37239235, 2023). "Quercetin alleviates LPS-induced depression-like behavior and learning and memory impairment in rats by regulating BDNF-related imbalance of Copine 6 and TREM1/2 expression in the hippocampus." (PMID 34257681, 2021). "To gain further insights into the association of stress with depression and to explore the possible change of Copine 6 expression in stressed rats, we replicated the CUMS rat model and observed their depression-like behaviors." (PMID 30429764, 2018). "Considering the increasing evidence regarding the role of Copine 6 in the regulation of synaptic plasticity, the aim of the present study is to investigate Copine 6 expression in the hippocampus and the prefrontal cortex (PFC) in a stress-induced depression rat model." (PMID 30429764, 2018). "Furthermore, Pearson’s test revealed a potential relationship between the depression-like behavior, the plasma CRP concentration, and the protein expressions of BDNF, Copine 6, synapsin I, or synaptotagmin I in the hippocampus or the PFC." (PMID 30429764, 2018). "The results suggested that quercetin could alleviate LPS-induced depression-like behaviors and impairment of learning and memory in rats, the mechanism of which might be involved with regulating the BDNF-related imbalance expression of Copine 6 and TREM1/2 in the hippocampus and the PFC." (PMID 32009956, 2019).
epilepsy (2 papers, 2020 to 2024). A brain disorder characterized by episodes of abnormally increased neuronal discharge resulting in transient episodes of sensory or motor neurological dysfunction, or psychic dysfunction. "Copine 6 mRNA levels increased 6.6-fold in the neocortex of patients with epilepsy and 2.8-fold and 4-fold in the hippocampus and the cortex of epilepsy-induced rats, respectively." (PMID 38540677, 2024). "Copine 6 protein levels increased ~4.8-fold in the neocortex of patients with epilepsy and 2-fold and 2.5-fold in the hippocampus and the temporal cortex of epilepsy-induced rats, respectively." (PMID 38540677, 2024). "Moreover, although increased expression of copine 6 is observed after epilepsy development, further studies are necessary to determine if copine 6 is also involved in the epileptogenesis process." (PMID 33202963, 2020).
glioblastoma (2 papers, 2018 to 2021). The most malignant astrocytic tumor (WHO grade IV). "Evidence demonstrated that CPNE6 terminated their expression in glioblastomas." (PMID 30356407, 2018). "The report of CPNE6 in tumor progression in only limited in glioblastoma multiforme (GBM)." (PMID 34367247, 2021).
Anxiety (1 paper, 2016). Intense feelings of nervousness, tension, or panic often arise in response to interpersonal stresses. "The observed behavioural change was not based on altered anxiety or locomotor activity, or changes in foot-shock sensitivity between WT and Cpne6 KO mice." (PMID 27194588, 2016).
Down syndrome (1 paper, 2017). "Changes in copine 6 expression may be involved in neurodevelopmental disorders, as deformed dendritic spines and changes in spine density are hallmarks of many neurodevelopmental conditions, such as Down’s syndrome and FXS." (PMID 28775826, 2017).
endometrial cancer (1 paper, 2025). Primary or metastatic malignant neoplasm involving the endometrium (mucous membrane that lines the endometrial cavity). "In addition, CPNE6 has been found to be overexpressed in several types of cancers, including GBM, endometrial cancer, and lung cancers." (PMID 41562091, 2025).
non-alcoholic fatty liver disease (1 paper, 2018). "The decreased expression of Copine 6 in the hippocampus and the PFC of rats with non-alcoholic fatty liver disease was demonstrated in our previous study." (PMID 30429764, 2018).
schizophrenia (1 paper, 2017). A major psychotic disorder characterized by abnormalities in the perception or expression of reality. "In addition, we confirmed Cap2, Chgb, Cpne6, Lynx1, and Mbp; which were selected among gene products implicated in schizophrenia and neurological disorders by the DAVID algorithm (p < 2.35E-03)." (PMID 28344592, 2017).
tumor (3 papers, 2011 to 2025). "Although very little is known regarding CPNE6, other members of the copine family have been shown to promote tumor cell migration and repress NF-KB transcription." (PMID 21226949, 2011). "Additionally, CPNE6 was found to be differentially expressed in tumor cells, suggesting its potential role in cancer development and progression." (PMID 41562091, 2025). "Moreover, mRNA expressions of CA14, RPE65, IGSF1, SLC18 A2 and CPNE6 were significantly lower in PCa samples compared to benign samples, while HJURP, COMP, KRTAP5-1, VGF, SSTR1, LINC01612, NAALADL2-AS2, AMH and ARHGDIG were elevated in tumor samples (p < 0.05)." (PMID 40592939, 2025).
CPNE6 also shares sentences with these, for which no sentence is quoted: Alzheimer disease (1 paper); cancer (1); fragile X syndrome (1); itch (1); liposarcoma (1); lung carcinoma (1); memory impairment (1); neurodevelopmental disorder (1); neurological disorders (1); round cell liposarcoma (1).